RBMY1F (RNA binding motif protein Y-linked family 1 member F)
Description:
RNA-binding protein which may be involved in spermatogenesis. Required for sperm development, possibly by participating in pre-mRNA splicing in the testis.
Synonyms: YRRM2; MGC33094
Tractability: No criterion of Open Targets' tractability assessment is met for any kind of drug.
Gene: Protein-coding gene on chromosome Y (22,168,542 to 22,182,982, reverse strand). Ensembl gene ENSG00000169800.
Subcellular location: Nucleus
Subcellular location (Human Protein Atlas): Nucleoli; Nucleoplasm
Gene Ontology:
Molecular function: identical protein binding; protein binding; nucleic acid binding; RNA binding
Biological process: mRNA splicing, via spliceosome
Cellular component: spliceosomal complex; nucleus
Homologues: Orthologues: rat Rbmy1j (35% identical), macaque RBMY (35% identical), mouse Rbmyf9 (32% identical), mouse Rbmyf2 (32% identical), mouse Rbmyf3 (32% identical), mouse Rbmy (32% identical), mouse Rbmyf1 (32% identical), mouse Rbmyf5 (32% identical), mouse Rbmyf6 (32% identical), mouse Rbmyf7 (32% identical), mouse Rbmyf8 (32% identical), mouse Rbmyf4 (17% identical). Paralogues in human: RBMY1J (100% identical), RBMY1A1 (99% identical), RBMY1B (99% identical), RBMY1D (99% identical), RBMY1E (99% identical), RBMX (48% identical), RBMXL1 (46% identical), RBMXL2 (38% identical), RBMXL3 (31% identical), CIRBP (17% identical), RBM3 (14% identical), MSI1 (14% identical), and 24 more.
Diseases named in the same sentence as RBMY1F in open-access papers:
RBMY1F is named in the same sentence as 1 disease in open-access papers, as found by Europe PMC text mining. Sharing a sentence is not in itself a finding about the gene and the disease.
RBMY1F shares sentences with these, for which no sentence is quoted: Azoospermia (1 paper).